HNRNPL (heterogeneous nuclear ribonucleoprotein L)
Description:
Splicing factor binding to exonic or intronic sites and acting as either an activator or repressor of exon inclusion. Exhibits a binding preference for CA-rich elements. Component of the heterogeneous nuclear ribonucleoprotein (hnRNP) complexes and associated with most nascent transcripts. Associates, together with APEX1, to the negative calcium responsive element (nCaRE) B2 of the APEX2 promoter. As part of a ribonucleoprotein complex composed at least of ZNF827, HNRNPK and the circular RNA circZNF827 that nucleates the complex on chromatin, may negatively regulate the transcription of genes involved in neuronal differentiation. Regulates alternative splicing of a core group of genes involved in neuronal differentiation, likely by mediating H3K36me3-coupled transcription elongation and co-transcriptional RNA processing via interaction with CHD8.
Synonyms: HNRPL; P/OKcl.14; hnRNP-L
Tractability: PROTAC: UniProt records ubiquitination sites on it; ubiquitination databases record sites on it; its protein half-life has been measured.
Gene: Protein-coding gene on chromosome 19 (38,836,370 to 38,852,347, reverse strand). Ensembl gene ENSG00000104824.
Subcellular location: Nucleus, nucleoplasm; Cytoplasm
Subcellular location (Human Protein Atlas): Nucleoplasm
Pathways (Reactome):
Metabolism of RNA: Processing of Capped Intron-Containing Pre-mRNA; mRNA Polyadenylation; mRNA Splicing - Major Pathway
Disease: Dengue Virus-Host Interactions
Gene Ontology:
Molecular function: pre-mRNA intronic binding; protein binding; RNA binding; transcription cis-regulatory region binding; nucleic acid binding
Biological process: negative regulation of DNA-templated transcription; regulation of alternative mRNA splicing, via spliceosome; RNA processing; mRNA processing; regulation of RNA splicing
Cellular component: chromatin; cytoplasm; extracellular exosome; membrane; nucleoplasm; nucleus; ribonucleoprotein complex; ribonucleoprotein granule; pronucleus; synapse
Genetic constraint (gnomAD): Loss-of-function variants: 1 observed, 46.02 expected, observed/expected ratio (o/e) 0.0217, 90% interval 0.007 to 0.1. The upper end of that interval is the gene's LOEUF score, 0.1, which puts it in group 1 of 6, group 1 being the genes least tolerant of losing a copy. Missense variants: 291 observed, 573.3 expected, observed/expected ratio (o/e) 0.51, 90% interval 0.46 to 0.56. Synonymous variants: 258 observed, 217 expected, observed/expected ratio (o/e) 1.19, 90% interval 1.07 to 1.32.
Homologues: Orthologues: chimpanzee HNRNPL (100% identical), macaque HNRNPL (100% identical), dog HNRNPL (99% identical), pig HNRNPL (99% identical), guinea pig HNRNPL (99% identical), mouse Hnrnpl (98% identical), rabbit HNRNPL (96% identical), tropical clawed frog hnrnpl (79% identical), zebrafish hnrnpl (70% identical), zebrafish hnrnpl2 (68% identical), rat Hnrnpl (41% identical), Caenorhabditis elegans hrpl-1 (36% identical), and 1 more. Paralogues in human: HNRNPLL (50% identical), PTBP1 (27% identical), PTBP2 (25% identical), PTBP3 (25% identical), RBM20 (22% identical).
Diseases named in the same sentence as HNRNPL in open-access papers:
HNRNPL is named in the same sentence as 79 diseases in open-access papers, as found by Europe PMC text mining. Sharing a sentence is not in itself a finding about the gene and the disease. The quoted sentences say what the papers report.
prostate carcinoma (36 papers, 2017 to 2026). A carcinoma that arises from epithelial cells of the prostate gland. "The heterogeneous nuclear ribonucleoprotein L (HnRNP L), a protein involved in the regulation of mRNA splicing, is reported to be linked to cancer resistance and immune escape in prostate cancer." (PMID 38539569, 2024). "HNRNPL directly regulates the AS of various RNAs, including those encoding the AR as well as the key lineage-specific prostate cancer oncogene." (PMID 36052164, 2022). "Moreover, the HNRNPL-regulated splicing targets were prominently associated with the overexpressed gene signatures in prostate cancer, indicating that these HNRNPL targets may collectively contribute to cancer progression." (PMID 30939845, 2019). "By high-throughput CRISPR screening in vivo, RBP HNRNPL (heterogeneous nuclear ribonucleoprotein L) was identified as a prostate cancer-dependent gene." (PMID 40290118, 2025). "Genome-wide CRISPR-Cas9 knockout screening in prostate cancer cells identifies HNRNPL, which directly regulates alternative splicing and circular RNA formation." (PMID 39180763, 2024). "In prostate cancer, heterogeneous nuclear ribonucleoprotein L (HnRNPL) inhibition reduced PD‐L1 expression, increased IFN‐γ production, and induced ferroptosis in CRPC cells through the STAT1/SLC7A11/GPX4 signalling pathways axis." (PMID 38594879, 2024). "For instance, in prostate cancer, heterogeneous nuclear ribonucleoprotein L-catalyzed upregulation of circCSPP1 leads to the induction of autophagy via the circCSPP1/miR-520 h axis, thereby regulating prostate tumor progression." (PMID 38956466, 2024). "CircRNA formation via back-splicing is also mediated by heterogeneous nuclear ribonucleoprotein L (HNRNPL) which is required for prostate cancer growth in vitro and is aberrantly expressed in human prostate tumors." (PMID 37587333, 2023). "Genome-wide CRISPR screen identifies HNRNPL as a prostate cancer dependency regulating RNA splicing." (PMID 38098508, 2023). "In prostate cancer, PD-L1 was positively related to heterogeneous nuclear ribonucleoprotein L (HnRNPL), which overexpressed and consequently enhanced the mRNA stability of YY1, in turn generating pro-proliferative and anti-apoptotic effects." (PMID 36335094, 2022). "HNRNPL was previously confirmed to promote circRNA formation in prostate cancer, and the binding of HNRNPL within the flanking introns of circFAM73A was also verified via motif scanning and RIP assays, strongly indicating its role in circFAM73A formation." (PMID 33731207, 2021). "The heterogeneous nuclear ribonucleoprotein L (HNRNPL) also regulated circRNAs formation via back splicing by genome-wide CRISPR screen in human prostate cancer." (PMID 32061256, 2020). "Specifically, 47 out of 119 cassette exon events occurring upon LNA-mediated DSCAM-AS1 silencing were observed also upon siRNA-mediated silencing of hnRNPL in LNCaP, an androgen receptor-positive prostate cancer cell line." (PMID 32503257, 2020). "hnRNPL was also involved in prostate cancer progression through regulating the alternative splicing of a set of RNAs, including those encoding androgen receptor, the key lineage-specific oncogene of prostate cancer." (PMID 31856843, 2019). "Depletion of HNRNPL has been reported to significantly suppress cell proliferation of bladder cancer and prostate cancer cells." (PMID 31355266, 2019). "Comprehensive analysis of HNRNPL-dependent alternative splicing processes in prostate cancer cells identified direct HNRNPL-regulated signals." (PMID 30939845, 2019). "Knockdown of HNRNPL in human prostate cancer cell lines also increased apoptosis." (PMID 40944391, 2026). "Similarly, in prostate cancer cells, the heterogeneous nuclear ribonucleoprotein L (HnRNP L) induces the stable expression of YY1, which in turn upregulates the production of PD-L1." (PMID 38853203, 2024).
prostate carcinoma (continued). "HNRNPL: One of the crucial splicing factors, heterogeneous nuclear ribonucleoprotein L (HNRNPL) is involved in the regulation of alternative splicing and circular RNA formation in prostate cancer cells." (PMID 34449657, 2021). "Finally, our previous work confirmed that SNHG1 triggers EMT pathway through directly binding to hnRNPL in the development of prostate cancer." (PMID 33542227, 2021). "For example, HNRNPL could directly regulate RNA processing, including androgen receptor RNA alternative splicing and circular RNA formation in prostate cancer." (PMID 32669100, 2020). "Importantly, next‐generation sequencing has suggested HNRNPL as a key regulator of prostate cancer via modulating the alternative splicing of multiple RNAs such as the core oncogene androgen receptor." (PMID 32915499, 2020). "SNHG1 is reported to bind to certain RBPs like heterogeneous nuclear ribonucleoprotein L (HNRNPL) and matrin 3 (MATR3) and to promote the progression of prostate cancer (PCa) as well as neuroblastoma." (PMID 40510136, 2025). "In prostate cancer, SNHG1 promotes EMT processes by competitively binding to hnRNPL, preventing E-cadherin translation." (PMID 38331968, 2024). "The use of genome-wide CRISPR-knockout screens found that the heterogeneous nuclear ribonucleoprotein L (HNRNPL) gene is essential and is required for prostate cancer cell growth." (PMID 36969009, 2023). "Recently, it was reported that SETD2 regulates the deposition of H3K36me3 by interacting with hnRNPL, and that SETD2 suppresses metastatic progression of prostate cancer by methylating EZH2 to lead its degradation." (PMID 35216000, 2022). "In addition to this, lncRNA SNHG1 and RNA binding protein hnRNPL were found to form a complex and coregulate CDH1 to enhance prostate cancer growth and metastasis." (PMID 35846429, 2022). "Furthermore, the SNHG1/hnRNPL complex lead to a downstream of E-cadherin via binding to its mRNA, which promotes EMT in prostate cancer." (PMID 33542227, 2021).
breast carcinoma (19 papers, 2017 to 2025). "LncRNA MEG3 regulates chondrogenic differentiation by inhibiting TRIB2, which is achieved by binding with EZH2 as well as LINC02273; it is associated with hnRNPL, which promotes metastasis of breast cancer by increasing AGR2 transcription." (PMID 38017487, 2023). "We investigated the synergic role of the circRNA circCDYL and the splicing factor hnRNPL in modulating alternative splicing and isoform switch in breast cancer cells, with a focus on circCDYL and hnRNPL‐mediated isoform switch events involving the CDYL gene." (PMID 40702809, 2025). "Mechanistically, the oncogenic action of DSCAM-AS1 was demonstrated to interact with nuclear ribonucleoprotein hnRNPL in breast cancer cells, which has been found to facilitate progression of breast cancer and induce resistance to tamoxifen." (PMID 35885035, 2022). "For example, the complex of lncRNA, DSCAM-AS1, and HNRNPL are necessary for breast cancer progression and tamoxifen resistance." (PMID 34543262, 2021). "Estrogen-induced lncRNA DSCAM-AS1 is reported to be highly and specifically expressed in luminal-subtype breast cancer and mediates the development of ER+ breast cancer, and tamoxifen resistance through the interacting protein, hnRNPL." (PMID 33098638, 2020). "Consistently, knockdown of hnRNPL significantly inhibited, while ectopic overexpression of hnRNPL enhanced, breast cancer cell migration and invasion, supporting a metastasis-promoting role of hnRNPL in breast cancer." (PMID 31856843, 2019). "Here we demonstrated that hnRNPL-promoted breast cancer metastasis was dependent on, at least in part, stabilizing LINC02273." (PMID 31856843, 2019). "Overall, hnRNPL mRNA expression was relative stable in breast cancer samples (RPKM mean = 138, mean fold change = 4.7, coefficient of variation = 20.8% )." (PMID 31856843, 2019). "We further showed that LINC02273 was stabilized by hnRNPL, a protein increased in metastatic lesions, in breast cancer cells." (PMID 31856843, 2019). "DSCAM-AS1 mediates tumour progression and tamoxifen resistance in breast cancer through interacting protein hnRNPL." (PMID 29757368, 2018). "Also, a strong positive correlation between HNRNPL and ITGβ3 expression was seen in breast cancer patients." (PMID 40060410, 2025). "Moreover, there is a positive correlation between NRF2 mRNA expression and HNRNPL mRNA expression in basal breast cancer patients." (PMID 40060410, 2025). "Taking it one step further, therapeutic strategies that inhibit circular RNA formation via HNRNPL upon radiotherapy may decrease distant recurrence in breast cancer patients." (PMID 40060410, 2025). "For example, the β-deletion has been shown or speculated to be regulated by RMB10 in pancreatic cancer; NOVA1/PTBP1 in lung cancer; SRSF11, hnRNPH2, and hnRNPL in breast cancer; and MCPH1/BRIT1 in ovarian cancer." (PMID 33924498, 2021). "Although the manner in which DSCAM-AS1 functions in breast cancers remains unclear, the RNA-binding protein heterogeneous nuclear ribonucleoprotein L (hnRNPL) is required for DSCAM-AS1 activity in MCF7 and T47D cells." (PMID 32486413, 2020). "We found hnRNPL enhanced AGR2 transcription in breast cancer cells." (PMID 31856843, 2019). "Taken together, our results strongly support that hnRNPL may promote breast cancer metastasis through stabilizing LINC02273." (PMID 31856843, 2019). "Interestingly, HNRNPL loss induces the exclusion of exon 12 in NUMB and the inclusion of exon 11 in EXOC1, suggesting a cooperative role of these two proteins in splicing regulation during breast cancer metastasis." (PMID 40323145, 2025). "Despite the interaction between DSCAM-AS1 and hnRNPL at BCL2, 3′UTR deserves further experimental validations, and DSCAM-AS1 represents a good candidate to regulate this process in luminal breast cancer cells." (PMID 32503257, 2020).
breast carcinoma (continued). "Finally, we found that HNRNPL and SRSF7 were both significantly overexpressed in basal tumors when compared to other breast cancer subtypes and to normal tissue samples." (PMID 38664594, 2024). "For instance, one rG4-binding protein, HNRNPL, recruited by rG4-containing TCNE transcripts, could increase the stability of transcripts and subsequently influence gene expression, contributing to breast cancer metastasis." (PMID 40427520, 2025). "For example, one RBP, HNRNPL, recruited by rG4-containing TCNE transcripts, was demonstrated to be an rG4-binding protein in the QUADRatlas database, which could regulate gene expression via its impact on transcript stability and contribute to breast cancer metastasis." (PMID 40427520, 2025).
bladder cancer (12 papers, 2017 to 2025). "Importantly, HNRNPL has been recently associated with aggressiveness and poor prognosis in different malignances such as colorectal cancer, hepatocellular carcinoma, and bladder cancer." (PMID 29744371, 2018). "CircMGA enhances the infiltration of CD8+ T cells in bladder cancer by increasing the expression of CCL5 through interaction with heterogeneous nuclear ribonucleoprotein L (HNRNPL)." (PMID 40710359, 2025). "LNMAT1 epigenetically activates CCL2 expression by recruiting hnRNPL to the CCL2 promoter in bladder cancer." (PMID 32019566, 2020). "In this study, we demonstrated that LNMAT1 epigenetically upregulated CCL2 expression in bladder cancer cells by interacting with hnRNPL to promote H3K4me3 of the CCL2 promoter." (PMID 30237493, 2018). "Heterogeneous nuclear ribonucleoprotein L (hnRNP-L) is a promoter of various kinds of cancers, but its actions in bladder cancer (BC) are unclear." (PMID 28088793, 2017). "For instance, hnRNPL could promote lymphatic metastasis of bladder cancer through binding with LNMAT1." (PMID 31856843, 2019). "And lncRNA RBAT1 promotes tumor initiation by interacting with and activating HNRNPL and E2F3 in bladder cancer, respectively." (PMID 39539669, 2024). "Next, the regulatory effect of hnRNPL on CCL2 expression was examined with ELISA and qRT-PCR assays, which showed that CCL2 expression was decreased in hnRNPL-silenced bladder cancer cells." (PMID 30237493, 2018).
lung carcinoma (8 papers, 2013 to 2024). "RNA-binding protein HNRNPL has been previously shown to associate with tumorigenesis in liver and lung cancer, and results show that KER_793 matches with its binding motif RNCMPT00027." (PMID 31703384, 2019). "In this support, interaction of hnRNPK, hnRNPC, hnRNPL and hnRNPA2/B1 with hnRNPD in cervical and lung cancer cells has been reported earlier." (PMID 26318153, 2015).
colorectal cancer (7 papers, 2011 to 2025). A primary or metastatic malignant neoplasm that affects the colon or rectum. "Among them, the most represented RBP family was the hnRNPs, including hnRNPA2B1, whose interaction with circCDYL was characterized in colorectal cancer, and hnRNPL, with 40 candidate binding motifs on the circRNA sequence." (PMID 40702809, 2025). "HNRNPL expression levels were high in both normal colorectal and colorectal cancer tissues." (PMID 39023715, 2024). "It is possible that HNRNPL, PABPC1, RPS4X, and RPS7 correlate with oxaliplatin resistance but are not directly involved biochemically in the process of resistance in colorectal cancer cell types." (PMID 22118625, 2011). "Among these hub genes, HNRNPL and HNRNPH1 genes may be molecular markers for early colorectal cancer diagnosis in MSS.TRA2A and SRSF6 may play important roles in PCRC metastasis." (PMID 39023715, 2024).
hepatocellular carcinoma (7 papers, 2017 to 2024). A malignant tumor that arises from hepatocytes. "In hepatocellular carcinoma, the lncRNA SPRY4-IT1 associates with HNRNPL to promote growth and metastasis through the tumor necrosis factor (TNF) pathway." (PMID 34543262, 2021). "For example, by forming a complex with heterogeneous nuclear ribonucleoprotein L (HNRNPL), cytoplasmic lncRNA CASC9 regulates genes linked to AKT signaling in hepatocellular carcinoma." (PMID 32669100, 2020). "Furthermore, SNHG6 can interact with heterogeneous nuclear ribonucleoprotein L (HNRNPL) and polypyrimidine tract binding protein 1 (PTBP1) to promote the progression of hepatocellular carcinoma." (PMID 37004005, 2023).